TNF (tumor necrosis factor)
Diseases named in the same sentence as TNF in open-access papers (continued):
Sharing a sentence is not in itself a finding about the gene and the disease.
Cognitive impairment (continued). "Consequently, aged rats but not young rats had significant increases in levels of ROS, expression of inflammatory cytokines TNF-α and IL-1β, activation of NF-κB and microglia in the hippocampus, and cognitive impairment following surgery." (PMID 36819786, 2023). "Similarly, excessive level of Escherichia coli in the gut microbiota stimulates microgliosis and activates TNF-α, IL-12, and IL-6, eventually resulting in cognitive impairments." (PMID 37237920, 2023). "Notably, only 3,6-DT demonstrated efficacy in preventing cognitive impairment and reducing brain TNF-α gene expression levels." (PMID 38201258, 2023). "However, in brain tissue from mdx mice, heightened levels of pro-inflammatory interleukin (IL)-1β and tumor necrosis factor (TNF)-α associated with several neurological diseases have been found and several cognitive deficits have also been observed." (PMID 37108685, 2023). "Here we proposed important ideas of IL‐1β, TNF‐α, and IL‐4; as the underlying CRCI pathway for coping with persistent psychological distress, as well as the potential evidence of psychological intervention to relieve cognitive impairment." (PMID 36965094, 2023). "Evidence supports that the elevation of DOX-induced inflammatory mediators in this study, like TNF-α and NF-κB, also mediate apoptosis regulation, particularly Caspase-3 activation, and might lead to neuronal damage and cognitive deficits." (PMID 37511284, 2023). "In conclusion, Yisui multipurpose soup could effectively protect D-galactose-induced neuronal cell cognitive impairment by orchestrating expressions of the inflammatory factors TNF-α, iNOS, NO, and IL-1β and the apoptosis-related proteins Bcl-2 and Bax." (PMID 35754679, 2022). "A high level of TNF is a potential marker of the progression of cognitive impairment to AD." (PMID 36778591, 2022). "Dexmedetomidine could reduce the incidence of cognitive impairment after intestinal I/R injury, which may be related to decreased levels of inflammatory cytokines IL-1β, IL-6, C-reactive protein, and TNF-α." (PMID 35945306, 2022). "Diosmin may aid to ameliorate scopolamine-induced synaptic plasticity disruption and cognitive impairments by reducing the expression of the pro-inflammatory cytokine TNF in the rat hippocampus." (PMID 35625813, 2022). "We suggest that such oligomer-induced microglial dysfunction in the ACC and hippocampus may alter the neuronal activity via the action of TNF-α on neurons, leading to cognitive deficits." (PMID 36078036, 2022). "This study showed that CHRE improved cognitive impairments in Aβ1–42-induced rats through decreased Aβ1–42 protein levels and neuroinflammation, particularly the expressions of CD11b-positive microglia, IL-1β, and TNFα in the cerebral cortex and hippocampus." (PMID 35439990, 2022). "A study of recurrent neonatal seizures (RNS) has shown an evident up-regulation in the expression of TNF-α and IL-1β as well as a remarkable increase of NF-κB activity in both the cortex and hippocampus of the RNS brain, which were associated with cognitive impairment." (PMID 35974336, 2022). "EPHB2 TNF-α/nuclear factor-kappa B signaling has been reported to worsen cognitive impairment." (PMID 35646066, 2022). "The combined use of ginsenoside Rb1 and Rg1 reduces brain Aβ production by modulating multiple factors, including the NLRP3 inflammasome, TNF-α, oxidative stress, astrocytes, and microglial plasma cell activation, and improves cognitive impairment in SAMP8 mice." (PMID 36506569, 2022). "In addition, peripheral inflammation contributes to AD progression and is correlated to cognitive deficits, specifically at MCI stage, and increased peripheral production of IL-1β and TNFα is associated with a higher risk of AD." (PMID 35248147, 2022). "However, clinical trials using anti-TNF-α agents for preventing long-term cognitive impairment are still sparse." (PMID 35603184, 2022).
Cognitive impairment (continued). "Similarly, early inhibition of TNFα in 3xTgAD mice prevents cognitive impairment, concomitantly reduces CNS infiltration of peripheral blood leukocytes and reduces Aβ-plaque formation." (PMID 35248147, 2022). "Importantly, the cognitive impairment was alleviated by treatment with anti-TNF-α antibodies and led to a reduction of biochemical alterations produced by Aβ1–40." (PMID 36550479, 2022). "Another experimental study reported that in Aβ42-induced rats, β-asarone improved cognitive impairment and alleviated Aβ deposition by protecting astrocytes, which was possibly achieved by reducing the levels of TNF-α and IL-1β and then downregulating AQP4 expression." (PMID 35215287, 2022). "Consistently, we also showed the potential link on the occurrence of cognitive impairment and the elevation of IL-6 and TNF-α in peripheral blood of preterm rats, which might be induced by the disrupted intestinal microflora." (PMID 36061856, 2022). "Furthermore, studies have reported that elevated TNF-α can lead to memory impairment and cognitive deficit, which contributes to different brain disorders, including AD, trauma, and Parkinson’s disease." (PMID 36143409, 2022). "Furthermore, cognitive impairment caused significantly decreased levels of 5-HT, GABA, and BDNF, and increased levels of GR, CRH, IL-6, and TNF-α in rat blood." (PMID 36061856, 2022). "TNF-α and IL-1β in the ischemic brain can reportedly induce the production of IL-6, and increased IL-6 levels in the serum and cerebrospinal fluid are related to cognitive impairment." (PMID 34457113, 2021). "Indeed, due to the well-known roles of TNF-α in the stimulation of Aβ overproduction and tauopathy and AD-like cognitive dysfunction, anti-TNF-α treatment has been shown to be effective in rescuing cognitive impairments and pathological changes in AD." (PMID 34030135, 2021). "TNF-α is known to inhibit neurogenesis and influence Aβ pathologies and cognitive deficits." (PMID 34881081, 2021). "Notably, it has been demonstrated that onjisaponin B can prevent cognitive impairment in d-gal induced aging in rats by regulating inflammatory mediators (TNF-α, IL-6, and IL-1β) and oxidative stress-related indicators (MDA, SOD, GSH, and GSH-PX)." (PMID 33878733, 2021). "Moreover, miR-485-3p ASO treatment reduced secretion of proinflammatory cytokines, including IL-1β and TNF-α, and eventually relieved cognitive impairment." (PMID 34884940, 2021). "Therefore, TNF-α appears to play a different role in the long-term cognitive deficits observed in our orthopaedic surgery models of POCD." (PMID 33980934, 2021). "Studies showed that the levels of IL-6 and TNF-α were elevated in the brain and in cerebrospinal fluid (CSF) of AD patients, while IL-6 may be a predictor for the severity of cognitive defects." (PMID 34706756, 2021). "Similarly to IL-1β, also TNFα, at levels over the physiological range, leads to hippocampal LTP impairment associated with depressive-like behavior and cognitive deficits in animal models." (PMID 33732142, 2021). "The MGCs, Mφs, and sera of the PARK2 mouse model displayed decreased expression of parkin and its link to the increased generation of pro-inflammatory cytokines and chemokines (e.g., IFNβ1, TNFα, IL-1β, IL-12, IL-13, IL-17, CCL2, and CXCL1), loss of DA neurons, and cognitive defects in PD." (PMID 34239490, 2021). "However, oral administration of NK210, NK219, or Mx decreased cognitive impairment-like behaviors, NF-κB+/Iba1+ cell population, and TNF-α and IFN-γ expression in the hippocampus, while BDNF+/NeuN+ cell population and IL-10 expression increased." (PMID 34667205, 2021). "Furthermore, strength training lasting 28 weeks increased IL-10 levels and slight maintained TNF-α levels in older women with cognitive impairment." (PMID 33936044, 2021).
Cognitive impairment (continued). "The expression of mTNF-α (a precursor of TNF-α) in microglia cells increases during propofol anesthesia and may mediate propofol-induced neurotoxicity and cognitive impairment in surgical or critically ill patients." (PMID 34250089, 2021). "In an animal study, Sun and his colleagues found that Rehmannioside A could attenuate cognitive deficits in rats with VD through reducing the release of proinflammatory cytokines, including TNF-α, IL-1β, and IL-6." (PMID 32617097, 2020). "However, an in-depth understanding of the effects of microglial TNF on synaptic functions and of the mechanisms underlying its actions may provide important insights for the development of novel therapeutic strategies aimed to limit neuronal loss and to improve cognitive deficits in patients." (PMID 32977412, 2020). "Proinflammatory cytokines IL-1β, IL-6, and TNF-α independently resulted in cognitive impairment." (PMID 32063834, 2020). "Increased TNF-α levels transform the physiological actions of cytokines into adverse ones, which may contribute to cognitive deficits." (PMID 32754015, 2020). "Indeed, chronic exercise ameliorates cognitive impairment in wild-type mice by reducing the expression of hippocampal TNF and increasing the expression of TNFR1 and TNFR2." (PMID 32977412, 2020). "However, we found that SAH indeed enhanced neuroinflammation in the hippocampus, as evidenced by the enhanced expression of TNF-α and the activation of microglia, and induced cognitive impairment in rats." (PMID 32754015, 2020). "Since TNF and TNFR interactions are proposed to play a role in neuronal growth, the disruptions of these interactions may contribute to cognitive impairment, as seen in patients with progranulin mutations." (PMID 32992926, 2020). "Multiple studies detected elevated TNF-α levels in both mild cognitive impairment (MCI) and AD." (PMID 32296418, 2020). "Furthermore, a role for inflammation i.e., increased levels of cytokines including interleukin-6 and tumor necrosis factor (TNF), has also been suggested as a possible causal pathway between anxiety and cognitive impairment." (PMID 32477097, 2020). "Numerous studies have found that high levels of cytokine expression (IL-1β, IL-6, and TNF-α), glial activation, hippocampal microgliosis, and cognitive deficits are ameliorated by the administration of NSAIDS such as ibuprofen, paracetamol, and parecoxib in animal models." (PMID 32738920, 2020). "A prior study demonstrated that the inhibition of TNF-α synthesis can significantly reverse hippocampus-dependent cognitive deficits induced by chronic neuroinflammation, suggesting that TNF-α is a critical mediator of chronic neuroinflammation-induced neuronal dysfunction and cognitive impairment." (PMID 31297084, 2019). "Activated glia stimulated by Aβ has been reported to upregulate the expression of several proinflammatory chemokines and cytokines including IL-1β, IL-6, and TNF-α, which could result in an increase of Aβ production, neuronal death, and cognitive deficits." (PMID 30871577, 2019). "Cognitive impairments have also been demonstrated in transgenic mice over-expressing TNF." (PMID 30823516, 2019). "The synthesis and release of proinflammatory cytokines such as IL-1β, IL-6, and TNF-α contribute to cognitive impairment by affecting cognitive processes such as synaptic plasticity, neurogenesis, neuromodulation, memory consolidation, and long-term potentiation (LTP)." (PMID 31565046, 2019). "Indeed, increased TNF-α in serum is associated with a worsen cognitive decline in AD and elevated concentrations of TNF-α in CSF increase the probability to evolve from a mild cognitive impairment (MCI) stage to dementia." (PMID 30885273, 2019). "Cognitive impairment is often described as an element of the so-called sickness behavior characterized by an increase in cytokines such as interleukin 1 (IL-1), interleukin 2 (IL-2), or tumor necrosis factor alpha (TNF-α)." (PMID 31044590, 2019).
Cognitive impairment (continued). "The increase of TNF-α and IL-6 expression might trigger the disruption of BBB in the brain, which eventually caused cognitive impairment in the 8-week STZ rats." (PMID 29867440, 2018). "Greater severity of cognitive impairment measured using the ACE-R and the MMSE was associated with having a significantly lower level of IL-1beta, IL-2 and IL-4, and a higher level of IL-6 and TNF-alpha." (PMID 29248892, 2018). "To determine whether the inflammatory cytokines was involved in the cognitive impairment of the diabetic rats, we examined TNF-α, IL-1β and IL-6 mRNA expression in the brain." (PMID 29867440, 2018). "Further, we could not measure serum inflammatory mediators, including interleukin‐1, interleukin‐6, and tumor necrosis factor alpha, which have been reported to correlate with cognitive impairment." (PMID 30603112, 2018). "Using this model, we found that the levels of the pro-inflammatory cytokine, tumor necrosis factor α (TNFα) rise in 1-month old mice, 2 months before the onset of amyloid pathology and cognitive impairment, which becomes prevalent at 3 months of age in this model." (PMID 30135948, 2018). "In particular, Tumor Necrosis Factor-α (TNF-α) may interact with BDNF and cause cognitive impairment." (PMID 29896133, 2018). "The future studies should assess whether the BBB disruption and cognitive impairment are alleviated by blocking the TNF-α or IL-6 signaling." (PMID 29867440, 2018). "In further support of the neurotoxicity of TNF in AD, chronic neuronal TNF overexpression promotes brain inflammation and is detrimental for neuronal viability and these inflammatory events coincides with the appearance of cognitive deficits and synaptic dysfunctions." (PMID 29751683, 2018). "In addition, HBO2T reversed the HAE-induced upregulation of brain levels of proinflammatory cytokines including IL-1β, IL-6, TNF-α, and IF-γ as well as cognitive deficits." (PMID 30515398, 2018). "Moreover, TNF-induced glutamatergic transmission enhancement in the DG has been proposed as the synaptic counterpart of cognitive defects in EAE." (PMID 29861718, 2018). "In addition, TNFα knock-out mice show cognitive impairment (i.e., significant poorer learning, retention, and spatial learning), suggesting a strong role for TNFα on these mechanisms." (PMID 27012931, 2016). "Furthermore, NF-κB is also reported to execute the generation of proinflammatory cytokines such as IL-1β and TNF-α, which ultimately exacerbates neurotoxicity and cognitive deficits." (PMID 26881113, 2016). "For outcome measurements, brain water content was calculated in 12 studies, blood–brain barrier permeability was measured in seven studies, cognitive impairment was evaluated in two trials, the TNF-α level was detected in three studies and the NO level was detected in two studies." (PMID 26956181, 2016). "During the past few years, an increasing amount of evidence has supported the view that the excessive release of proinflammatory cytokines, including tumor necrosis factor α (TNFα), interleukin (IL)-1β and IL-6, is involved in cognitive impairment after surgery." (PMID 25887955, 2015). "In addition, there is a correlation of high TNF-α with a presence of low serum Klotho levels in HD patients with cognitive deficit as evaluated by Modified Mini Exam of Mental State (3MS) and Kidney Disease Quality of Life (KDQOL-sf) (unpublished data)." (PMID 25961830, 2015). "Furthermore, saffron significantly increased GSH, SOD, and CAT but remarkably decreased cognitive deficit, serum TNF-α, and induced nitric oxide synthase (iNOS) activity in hippocampus tissue." (PMID 25114929, 2014). "We will determine whether the peripheral surgical wounding without the influence of general anesthesia can still induce cognitive impairment in aged TNF-α, IL-6, or CD33 knockout mice in our future studies." (PMID 24796537, 2014).
Cognitive impairment (continued). "Belarbi found that the TNF-α synthesis inhibitor DT(3,6’dithiothalidomide) could significantly reverse hippocampus-dependent cognitive deficits induced by chronic neuro-inflammation." (PMID 24236147, 2013). "Moreover, we measured proinflammatory cytokines IL-1β, IL-6 and TNF-a concentration at a time when animals had significant cognitive impairments." (PMID 23613842, 2013). "Measuring TNFα at other time-points may be needed to determine the effects of isoflurane on TNFα expression and the role of TNFα in the isoflurane-induced cognitive impairment." (PMID 23251531, 2012). "Importantly, cerebrospinal fluid TNF-α levels correlated with cognitive impairment in Ugandan children." (PMID 23300448, 2012). "Indeed, systemic treatment of C57BL6/J mice with a neutralizing TNF-α antibody during the course of SF also prevented SF-induced increases in sleepiness and cognitive deficits." (PMID 22578011, 2012). "Animal and human studies suggest that pro-inflammatory cytokines such as interleukin (IL)-1, IL-6, and tumor necrosis factor (TNF)-α play a pivotal role in mediating sickness-related behavior and cognitive impairments by communicating peripheral inflammation to the brain." (PMID 22164271, 2011). "Additionally, IS is typically accompanied by the release of proinflammatory cytokines, such as interleukin-1β (IL-1β), IL-6, tumor necrosis factor-alpha (TNF-α), and IL-18,44 with neuroinflammation being a key pathological contributor to neuronal loss and cognitive impairment." (PMID 41550744, 2026). "In addition, TNFα has been implicated in synaptic dysfunction; peripheral TNFα production during preclinical EAE has been shown to induce synaptic instability in the primary somatosensory cortex, potentially contributing to sensory and cognitive impairments." (PMID 41480143, 2025). "Our findings suggest that serum TNF-α levels are elevated in MDD patients compared with healthy controls and are negatively correlated with immediate memory performance, indicating a potential role of TNF-α in the pathogenesis and cognitive impairment associated with MDD." (PMID 41392773, 2025). "Our results suggest that TNF-α, but not IL-6, is strongly linked to the risk of cognitive impairments in middle-aged women, indicating that TNF-α may be a critical marker of early neurodegenerative changes in this group." (PMID 40137151, 2025). "Furthermore, patients with mild cognitive impairment (MCI) have been identified to be at a greater risk of AD development due to a decrease of anti-inflammatory TGF-β and increased production of proinflammatory TNFα." (PMID 38689734, 2024). "Our findings supported our hypotheses; specifically, adolescents and young adults with MDD and severe suicidal symptoms had higher serum levels of proinflammatory cytokines (i.e., CRP and TNF-α) and exhibited greater cognitive deficits than did healthy controls." (PMID 38492052, 2024). "In terms of sources, omega-3 s from both dietary and supplementation sources may have positive health benefits, additionally, supplementation studies appear to demonstrate more consistent reductions in inflammatory markers including IL-6 and TNF-α amongst populations with mild cognitive impairment." (PMID 38371504, 2024). "Increasing evidence suggests that flavonoids could ameliorate allergic inflammation by suppressing IL-4 and IL-13 production following the release of basophils and histamine, and improve the cognitive impairment of patients with neurodegenerative disease by inhibiting TNF-α and IL-6 release." (PMID 37292198, 2023). "In addition, proinflammatory cytokines (interleukin 1β (IL-1β), interleukin 6 (IL-6), and tumor necrosis factor α [TNF-α]) are markedly increased in patients with mild cognitive impairment and AD, suggesting that intrathecal inflammation precedes AD development." (PMID 37163443, 2023).